ENSG00000266692
Synonyms: LOC124905069
Gene: Small nucleolar RNA gene on chromosome 21 (44,437,121 to 44,437,175, forward strand). Ensembl gene ENSG00000266692.
Gene Ontology:
Biological process: RNA processing
Cellular component: nucleolus
Homologues: Orthologues: mouse Gm22871 (84% identical), rat LOC120099063 (78% identical).